CD163 (CD163 molecule)
Diseases named in the same sentence as CD163 in open-access papers (continued):
Sharing a sentence is not in itself a finding about the gene and the disease.
coronary artery disease (6 papers, 2014 to 2024). "Upregulation of human CD163 protein in detergent-resistant membranes from human peripheral blood monocytes was associated with coronary artery disease and myocardial infarction." (PMID 31900413, 2020). "A prior study provided evidence that the level of CD163 expressed on monocytes in individuals with coronary heart disease exhibited a positive correlation with low-density lipoprotein cholesterol." (PMID 37974098, 2023). "CD163 and FCGR3B were both linked to cardiovascular disorder of the myocardium and coronary heart disease." (PMID 31900413, 2020). "However, lots of DEGs were not previously reported in the investigation of VNS, such as CD163, CD48, DDit4, and ADAMTS1, which have been demonstrated close association with ischemic heart disease." (PMID 33981734, 2021).
coronary atherosclerosis (6 papers, 2015 to 2024). Atherosclerosis of the coronary vasculature. "Of note, high levels of soluble CD163 are a marker of coronary atherosclerosis and we have found in thalassemia patients CD163 concentrations significantly correlated with ferritin levels." (PMID 36699704, 2022). "HIV-infected patients who do not have a viral load in the blood plasma without ART are known as “elite controllers”; they have high coronary artery atherosclerosis and elevated immune activation, including high levels of soluble CD163 in plasma (sCD163)." (PMID 35269645, 2022).
dementia (6 papers, 2011 to 2023). Loss of intellectual abilities interfering with an individual's social and occupational functions. "In the brains of patients with HIV-associated dementia, CD163 was found to be expressed on microglia, and on perivascular macrophages near the blood-brain barrier, and CD163 is considered a marker for perivascular macrophages." (PMID 22666621, 2012). "CD163 co-expression on CD14+CD16++ monocytes has been proposed as a useful biomarker for HIV-1 disease progression and the presence of HIV associated dementia." (PMID 21625498, 2011).
embryonal rhabdomyosarcoma (6 papers, 2019 to 2025). A poorly circumscribed morphologic variant of rhabdomyosarcoma. "Evidence from embryonal rhabdomyosarcomas indicates that higher densities of CD163+ macrophages can correlate with better survival, potentially due to their interactions with other immune components, such as CD54+ microvessels, which enhance immune cell recruitment." (PMID 40423041, 2025).
endotoxemia (6 papers, 2014 to 2022). "Dexamethasone-conjugated anti-CD163 ADCs have especially shown promising results in simple endotoxemia and inflammatory disease models in rodents and pigs." (PMID 32752088, 2020). "To further examine the regulation of EV-CD163 in mice we analyzed the plasma levels of ectodomain CD163 and EV-CD163 in mouse models of experimental endotoxemia, sterile peritonitis and bacteraemia." (PMID 28084321, 2017). "Similarly, ADC composed of an anti-CD163 antibody and dexamethasone (Dex) exhibited highly potent anti-inflammatory activity in rat models of endotoxemia and non-alcoholic steatohepatitis, which was due to the selective targeting of M2 macrophages." (PMID 29324769, 2018). "Endotoxemia, macrophage overactivation and proinflammatory cytokines may induce the expression of CD163." (PMID 25187814, 2014). "The expression of SLA-DR was the lowest on the CD14+CD163− monocytes and it did not change significantly during endotoxemia regardless of the iNO + hydrocortisone treatment." (PMID 35566768, 2022). "The potency of dexamethasone conjugated to an anti-CD163 antibody was shown to be 50-fold higher compared to non-conjugated dexamethasone in in vivo endotoxemia models in both rat and pig." (PMID 32752088, 2020). "In contrast, no increase in exosome CD163 was detected in experimental endotoxemia and non-infectious sterile peritonitis." (PMID 28084321, 2017).
Gastric tumor (6 papers, 2018 to 2026). "A large number of studies are devoted to the analysis of the CD163+ macrophagecontent in gastric tumors, but the results are rather inconclusive." (PMID 36694901, 2022). "IL-6 can induce M2 macrophage differentiation through STAT3 activation and can enhance infiltration of CD163+CD206+ macrophages in gastric tumor tissue." (PMID 30283449, 2018). "Gastric tumor-derived MSCs have also been shown to increase the expression of CD163 in macrophages." (PMID 37048119, 2023). "In this work, we analyzed the content ofPU.1+, CD163+, and CD20+ in the stroma of gastric tumors and evaluated theirclinical and prognostic significance." (PMID 36694901, 2022). "Immunohistochemical staining for CD68 (pan-macrophage), CD163 (M2-like macrophage), and H. pylori in 200 samples (100 cases of cardia-GC [CGC] and 100 cases of non-cardia GC [NCGC]) was performed." (PMID 34926251, 2021).
heart failure (6 papers, 2014 to 2026). Inability of the heart to pump blood at an adequate rate to meet tissue metabolic requirements. "Research has suggested three potential biomarker genes (ASB14, CD163, and CCL5) associated with heart failure through the traditional protein–protein interaction algorithm." (PMID 40297163, 2025). "The obvious discrepancy between acute and chronic stages of heart failure cannot be easily explained but might be related to an increased clearance of sTWEAK from the circulation, for example, by its known scavenger receptor CD163 on monocytes." (PMID 24692845, 2014).
hemophagocytic syndrome (6 papers, 2013 to 2021). "CD163 is a scavenger receptor for hemoglobin and is increased in M2 macrophages associated with hemophagocytic syndromes." (PMID 34349768, 2021).
influenza (6 papers, 2015 to 2023). An acute viral infection of the respiratory tract, occurring in isolated cases, in epidemics, or in pandemics; it is caused by serologically different strains of viruses (influenzaviruses) designated A, B, and C, has a 3-day incubation period, and usually lasts for 3 to 10 days. "Severe influenza was also associated with increased expression of cleaved GSDMD, which colocalized with CD163 and with cytokeratin, reflecting pyroptosis of macrophages and alveolar epithelial cells respectively." (PMID 35271686, 2022). "Finally, we examined the expression of Il-1β and cleaved GSDMD in lung and its relationship to macrophages (CD163+) and alveolar epithelial cells (cytokeratin+) in uninfected macaques and those with lethal influenza by immunohistochemistry." (PMID 35271686, 2022).
interstitial lung disease (6 papers, 2016 to 2022). A diverse group of lung diseases that affect the lung parenchyma. "Increased CCL18 protein and higher CD163 mRNA were observed in lungs of patients with SSc-associated interstitial lung disease, suggestive of the presence of alternatively activated MØs." (PMID 28330499, 2017). "This study aimed to evaluate the clinical significance of soluble CD163 (sCD163) in PM/DM-related interstitial lung disease (ILD)." (PMID 28103926, 2017).
myocardial infarction (6 papers, 2013 to 2025). Gross necrosis of the myocardium, as a result of interruption of the blood supply to the area, as in coronary thrombosis. "Soluble CD163 (sCD163) has been associated with arterial inflammation and non-calcified plaques in human immunodeficiency virus (HIV)-infected individuals and has therefore been suggested as a predictive biomarker of myocardial infarction (MI)." (PMID 23692821, 2013). "Though the intake of hemoglobin by CD163 inducing a pathogenic or protective macrophage phenotype in AS remains controversial, the minor allele of the rs7136716 genotype could mediate microvessel density and impact the risks of CAD and myocardial infarction by regulating CD163 expression." (PMID 39759113, 2025). "Furthermore, it was reported that CD163-expressing macrophages not only regulated tissue regeneration after ischaemic injury induced by unilateral femoral artery ligation but also promoted ventricular functional recovery after myocardial infarction." (PMID 36082132, 2022). "Reduced transcription of CCL2, expression of CD163+ macrophages, and modulation of immune response factors, including IL-1, PBMC influx, TNF-α, GM-CSF levels, and CD73+ and CCR2+ monocytes, further support EV’s therapeutic potential for myocardial infarction." (PMID 38790361, 2024). "Conversely, the density of neither iNOS+ nor CD163+ macrophages was altered in a mouse model of myocardial infarction upon treatment with TRAM-34." (PMID 35455028, 2022).
nasopharyngeal carcinoma (6 papers, 2020 to 2024). A carcinoma arising from the nasopharyngeal epithelium. "Distribution of HO-1 and CD163 expression within the clinicopathological characteristics of nasopharyngeal carcinoma patients." (PMID 33589574, 2021). "The high degree of infiltration of giant cells in nasopharyngeal carcinoma indicates that the high expression of giant cells may be related to the prognosis of NPC, consistent with the previous literature that CD163+ giant and fine cells are associated with the poor prognosis of NPC." (PMID 36438903, 2022). "In nasopharyngeal carcinoma tissues, the number of ISG15+ CD163+ macrophages were significantly higher than that of non-cancerous nasopharyngeal epithelium, suggesting the infiltration of ISG15+ CD163+ macrophages relate to the development of NPC." (PMID 33424843, 2020).
ovarian tumor (6 papers, 2013 to 2022). "It had been reported that CD163 + Tim4 + macrophages resided in omentum form a protective niche to promote ovarian tumor spread." (PMID 36209225, 2022). "This approach has proven efficacious in preclinical models, with depletion of the murine CD163+ Tim4+ TRM subset via anti-CD163 mAb-coated cytotoxic liposomes found to reduce ovarian tumour burden in mice." (PMID 35020853, 2022). "Patients with a high density of ovarian tumor CD163+ ov-TAMs had a higher BMI (24 vs. 22, p = 0.03)." (PMID 34677277, 2021). "The data obtained in this study establishes the localisation and concentrations of CD163, hCAP-18, and lactoferrin in ovarian tumours and peripheral blood." (PMID 23339669, 2013). "Overall, we found that neither ovarian tumor densities of ov-CD68+ or CD163+ ov-TAMs nor the ratio of ovarian CD68+/CD163+ ov-TAMs was significantly associated with patient OS or PFS." (PMID 34677277, 2021). "In ovarian tumors, the number of CD68+, CD163+ TAMs is reported to show a stepwise increase from benign, borderline to malignant." (PMID 25499804, 2014). "However, even with these limits, we observed that the treatment of humanized ovarian tumor-bearing mice by murlentamab monotherapy tended to increase CD86+ blood cells and strongly decreased CD163+ blood cells, signing a monocyte/macrophage orientation towards an M1 anti-tumor profile." (PMID 33924378, 2021).
Pleural effusion (6 papers, 2015 to 2024). The presence of an excessive amount of fluid in the pleural cavity. "Flow cytometry-based detection of the frequency of CD163+CD14+ TAMs in pleural effusion samples had a sensitivity of 81.2 % and a specificity of 100 %." (PMID 38475858, 2024). "Within 12 h of PA-MSHA treatment, the amount of pleural effusion gradually decreased, and the cytotoxicity of CD163+ TAM-injured NK cells was restored." (PMID 38475858, 2024). "Results show pro-inflammatory cytokines were down-regulated significantly post antibiotic treatment in the pleural effusions and pleural macrophages up-regulated markers characteristic of M2 macrophages such as CD163 and CD206." (PMID 29101376, 2017). "Both membrane and soluble CD163 are markers of monocyte/macrophage activation, which were increased in patients with ATB, especially in pleural effusions." (PMID 31779590, 2019). "On the other hand, the CD163+14+ cell frequency in malignant pleural effusion was higher than that in non-malignant pleural effusion." (PMID 35237501, 2021). "Here, we found that the percentage of CD163+ TAMs in MPE was significantly higher than that in non-malignant pleural effusion (P<0.001)." (PMID 25871392, 2015). "So we detected surface CD163 expression on CD14+ macrophages derived from pleural effusion and peripheral blood in cancer patients or non-cancer patients by flow cytometry, respectively." (PMID 25871392, 2015).
renal carcinoma (6 papers, 2018 to 2025). A carcinoma arising from the epithelium of the renal parenchyma or the renal pelvis. "Notably, high infiltration of CD163+ TAMs in microenvironment has been reported to be associated with poor prognosis in RCC, promoting cancer cell proliferation through direct cell–cell interactions; this concept was already well known in the pre immunotherapy era of renal carcinoma." (PMID 38740647, 2024). "when neutrophils were co-cultured with PD-L1 knockout renal cancer cells, the CSF2-induced shift toward the N2 phenotype was partially attenuated, with decreased CD163/CD206 expression and a partial recovery of CD54/CD86 levels compared to co-culture with wild-type tumor cells." (PMID 41216204, 2025). "Interestingly, a unique feature in renal cancer was an abundance of CD68+/CD11c+ (2.2–13% of the CD68-mask) and CD68+/CD163+/CD11c+ (3.5–15%) pixels." (PMID 30619287, 2018).
renal fibrosis (6 papers, 2019 to 2025). A final common manifestation of a wide variety of chronic kidney diseases characterized by glomerulosclerosis and tubulointerstitial fibrosis. "MCP-1 is produced by renal cells and monocyte stimulated by inflammation, which may cause renal fibrosis through macrophage recruitment and direct induction of glomerular mesangial cell fibrosis, which increases synchronously with CD163 in patients with AAV." (PMID 33997033, 2021). "That may control CD163+ expression, which may induce renal fibrosis with irreversible renal damage." (PMID 39949667, 2025). "For instance, it has been postulated that the M2 macrophages responsible for renal fibrosis express CD206, CD204, and HLA-DRhigh; meanwhile, the ones responsible for tissue homeostasis express CD206, CD163, and HLA-DRlow." (PMID 38247813, 2024). "Given that our CM boosted macrophage phagocytosis and increased the expression of CD206 and CD163 while decreasing the level of HLA-DR and CD86, CM treatment for cisplatin-induced AKI might be beneficial to prevent the progression of renal fibrosis in vivo." (PMID 38247813, 2024).
ZIKV infection (6 papers, 2018 to 2022). "Accordingly, we found that, similar to human placental infection, ZIKV infection in the porcine placental mesenchyme is associated with an increased number of CD163-positive cells." (PMID 34578408, 2021). "Also, we have recently demonstrated that similar to human placental infection, ZIKV infection in the porcine placental mesenchyme is associated with the increased number of CD163-positive cells." (PMID 31725819, 2019). "Staining of placenta tissues for macrophage subtypes via CD68 (M1) and CD163 (M2) showed both populations were present, with an increase in M1 macrophages in the villous stroma during ZIKV infection." (PMID 29343712, 2018). "ZIKV-infected macrophages were further analyzed, which showed that the transcription of HLA-DRA, but not CD163, was upregulated indicating that ZIKV infection polarized THP-1-differentiated macrophages (M0) to proinflammatory M1 phenotype macrophages." (PMID 35446851, 2022).
acute liver failure (5 papers, 2013 to 2025). Rapid deterioration of liver function causing encephalopathy and coagulopathy. "Importantly, during sterile inflammation, DAMPs enhance CD163 expression, and its shedding can lead to significantly increased plasma concentrations in patients with acute liver failure and acute-on-chronic liver failure." (PMID 40565363, 2025).
acute myeloid leukemia (5 papers, 2018 to 2025). Acute myeloid leukemia (AML) is a group of neoplasms arising from precursor cells committed to the myeloid cell-line differentiation. "In acute myeloid leukemia, high CD163 expression has been linked to shorter survival, whereas CD68 showed no prognostic correlation." (PMID 41239536, 2025). "The number of CD163+ M2-like macrophages increases in bone marrow of patients with acute myeloid leukemia (AML) or multiple myeloma (MM)." (PMID 34359674, 2021). "Likewise, we were not able to detect CD209+CD14+CD163+ ercDCs among PBMC of healthy donors or patients by flow cytometry (data not shown) and the ercDC score was very low in samples of acute myeloid leukemia of the TCGA collection compared to ccRCCs (not shown)." (PMID 36291154, 2022).
acute respiratory distress syndrome (5 papers, 2020 to 2025). Progressive and life-threatening pulmonary distress in the absence of an underlying pulmonary condition, usually following major trauma or surgery. "Interestingly, CD163‐enriched macrophages were reported to have a pro‐fibrotic phenotype and accumulate in the lungs specifically in areas of fibrotic tissue remodeling in patients with severe COVID‐19‐associated acute respiratory distress syndrome." (PMID 39821970, 2025).
anemia (5 papers, 2013 to 2024). A reduction in the number of red blood cells, the amount of hemoglobin, and/or the volume of packed red blood cells. "Our study indicated that anemia in combination with a >2.5-fold increase in the percentage of CD163+EPOR+ TAMs had the worst prognosis." (PMID 32908942, 2020). "A ≥2.5-fold increase in infiltration of CD163+EPOR+ TAMs was associated with malignant tumor phenotypes, such as the number of lung metastases, maximal diameter of lung metastases and pathologic grade as well as anemia." (PMID 32908942, 2020). "Because EPOR was expressed by TAMs and anemia can induce EPO secretion, which can activate the EPO-EPOR signal to promote the protumor functions of CD163+EPOR+ TAMs." (PMID 32908942, 2020).